TSLP (thymic stromal lymphopoietin)
Diseases named in the same sentence as TSLP in open-access papers (continued):
Sharing a sentence is not in itself a finding about the gene and the disease.
allergic disease (continued). "The negative relationship between expression of TSLP and respiratory symptoms/allergic diseases has been established in our and previous studies." (PMID 33836808, 2021). "A possible link between histamine and TRPA1 signaling might be thymic stromal lymphopoietin (TSLP), a known progressor of allergic diseases." (PMID 34439832, 2021). "The researchers confirmed that the mice’s exposure to transdermal TSLP without coexistent antigen did not cause inflammation in the airways, while in mice that were sensitized with OVA alone, the allergy did not extend to the respiratory tract." (PMID 34301307, 2021). "Specific associations were found when examining hematological effects but not for indicators of allergic diseases (i.e., IgE, TSLP and IL-33)." (PMID 34712855, 2021). "This was rather surprising considering that IL-33 but not TSLP was previously indicated as having a critical, non-redundant role in allergy." (PMID 29896198, 2018). "Basolateral challenge of the epithelium with HIS induced upregulation of pro-inflammatory cytokines as IL-6 and IL-8; however, other major cytokines involved in the allergic reaction (IL-25, IL-33, and TSLP) were not detectable in the epithelium with or without the addition of HIS." (PMID 38933682, 2024). "Although TSLP is primarily expressed in skin keratinocytes, lung, and gut epithelial cells, the function of TSLP in the gut has not yet been clearly identified in contrast to its role in allergy and infection in the lung and skin." (PMID 35707544, 2022). "Collectively, these studies suggest that in mice TSLP has an important role during the early development of Th2 immune responses, whereas its role at later stages of allergic disease may not be as critical for maintaining the Th2-driven allergic disease." (PMID 23437132, 2013). "In addition to therapeutic targeting of TSLP and IL33, local application of non-pathogenic LPS may be a rational strategy to prevent allergies." (PMID 27826297, 2016). "Our data point to a synergistic action of TSLP and IL-33 on OX40L expression, as also more recently shown in a rhinovirus-mediated allergic reaction to aeroallergen, rather than an exclusive IL-33-mediated effect as previously suggested." (PMID 29896198, 2018).
atopic dermatitis (203 papers, 2008 to 2026). "TSLP receptor-deficient mice exhibit attenuated allergic immune responses, and overproduction of TSLP in the skin causes atopic dermatitis-like symptoms." (PMID 41576104, 2026). "This study provides mechanistic insight into how HIF activation shapes epithelial cytokine responses, offering a basis for understanding the pathogenesis of TSLP-associated diseases such as atopic dermatitis." (PMID 41576104, 2026). "For instance, the association of the TSLP SNP rs10073816 with atopic dermatitis persistence is strengthened when controlling for the IL7R SNP rs11567725." (PMID 39859044, 2025). "Levels of TSLP in the tissue of asthmatic patients or keratinocytes of acute and chronic lesions of atopic dermatitis patients have been linked to disease severity." (PMID 39940994, 2025). "The presence of IL-4 and IL-13 in skin lesions of atopic dermatitis is associated with the stimulation of thymic stromal lymphopoietin (TSLP) production in keratinocytes upon exposure to external substances." (PMID 37630370, 2023). "Another MAPK-activated signaling factor characterizing EBS, associated with pruritus and atopic dermatitis, is the DC-activating cytokine thymic stromal lymphopoietin (TSLP)." (PMID 34830328, 2021). "This suggests that TSLP has a role in causing itch in later stages of atopic dermatitis, but other mechanisms must be responsible for causing itch early on." (PMID 31782733, 2019). "In atopic dermatitis, epidermal keratinocytes have been linked to drive Th2-mediated inflammation by contributing to increased TSLP levels." (PMID 31226822, 2019). "Application of dTBP2 inhibited the mRNAs levels of proinflammatory cytokines such as IL-6 well as Th2-related cytokines/chemokines associated with pathogenesis of atopic dermatitis including IL-4, IL-5, IL-13, TSLP, MCD, and TARC." (PMID 28134765, 2017). "In the skin lesions of atopic dermatitis (AD), keratinocytes release large quantities of thymic stromal lymphopoietin (TSLP), causing unfavorable inflammation along with skin damage." (PMID 25171086, 2014). "Thymic stromal lymphopoietin (TSLP) is an epithelial-derived cytokine that induces type 2 immune responses through dendritic cell activation, and its aberrant regulation is implicated in TSLP-associated inflammatory disorders including atopic dermatitis." (PMID 41576104, 2026). "An SNP in TSLP is associated with the prevalence and persistence of atopic dermatitis." (PMID 39859044, 2025). "We have identified RNAse7, the short form of thymic stromal lymphopoietin, and collagen XXIIIα as host proteins that contribute to the susceptibility to eczema herpeticum in patients with atopic dermatitis and modulate HSV-1 infection in human keratinocytes (78, –, 81)." (PMID 39945537, 2025). "In addition, TSLP has been linked to other conditions, including atopic dermatitis and eosinophilic esophagitis (EoE)." (PMID 39940994, 2025). "Although no significant variations in genotype frequencies were detected for IL-1β rs16944, significant associations were observed for TSLP rs2289277, particularly with conditions such as atopic dermatitis, food allergy, anaphylaxis, and combinations of these diseases." (PMID 39860604, 2025). "Silencing of miR-155-5p in atopic dermatitis mouse model reduced both the thickening of the epidermis and the expression of T helper type 2 (Th2) immune response-associated cytokines, thymic stromal lymphopoietin and interleukin-33, attenuating the overall allergic inflammation." (PMID 38562669, 2024). "Furthermore, in atopic dermatitis caused by Mi-2β deficiency, TSLP can directly act on local Tregs in the skin, promoting their proliferation and differentiation into effector Treg phenotypes." (PMID 39703503, 2024). "The extract also reduced the expressions of cytokines such as TSLP, IL-33, and IL-4, which are commonly expressed in atopic dermatitis and play roles in causing skin itching, suggesting that the extract may have had a notable effect on reducing itching." (PMID 37762597, 2023).
atopic dermatitis (continued). "Aberrant TSLP expression is a hallmark of atopic diseases, including atopic dermatitis (AD)." (PMID 33429916, 2021). "Thymic stromal lymphopoietin (TSLP) is a cytokine that is associated with atopic dermatitis." (PMID 33328984, 2020). "Mice injected intradermally with TSLP or transgenic for keratinocyte-specific TSLP expression display hallmark features of atopic dermatitis, including Th2 cytokine production, localized edema, acanthosis, hyperkeratosis and a dermal mononuclear cell infiltrate rich in eosinophils and mast cells." (PMID 23472158, 2013). "Thymic stromal lymphopoietin (TSLP) is associated with RA, allergic rhinitis and atopic dermatitis." (PMID 23190696, 2012). "This raises the intriguing question of whether TSLP is a cause or an effect of atopic dermatitis." (PMID 39206203, 2024). "The epidermal expression of TSLP, displaying response of keratinocytes to skin barrier damage, was found to be upregulated at as early as age 2 months in asymptomatic infants with family history of atopic dermatitis, correlating with higher risk of atopic dermatitis at 2 years of age." (PMID 36904070, 2023). "Background/Objectives: Thymic stromal lymphopoietin (TSLP) is central to the pathogenesis of atopic dermatitis (AD) and a promising therapeutic target." (PMID 42075836, 2026). "The objective of this research was to investigate the concentrations of TSLP and IL-1β in children with atopic eczema, FA, and anaphylaxis to healthy controls, assessing their potential as biomarkers for allergic conditions." (PMID 39860604, 2025). "In IL-4-stimulated keratinocytes, which mimic Th2-driven inflammation in atopic dermatitis, brief submicromolar pretreatment reduced TSLP expression at both mRNA and protein levels." (PMID 41304852, 2025). "For instance, variants at the 5q22 (TSLP/WDR36), 11q13 (LRRC32/C11orf30), and 12q13 (STAT6) loci are associated with asthma and atopic dermatitis and have been consistently associated with EoE risk 19,24." (PMID 40470207, 2025). "To further elucidate the therapeutic mechanisms of PCG in atopic dermatitis, we assessed epidermal thickness, serum TSLP levels, and calcium reactivity in dorsal root ganglion (DRG) neurons." (PMID 41009488, 2025). "In atopic dermatitis, keratinocytes from the compromised skin barrier release cytokines such as thymic stromal lymphopoietin (TSLP), IL-25, and IL-33, which activate APCs to express OX40L." (PMID 40155378, 2025). "- Atopic dermatitis is primarily Th2-driven, characterized by IL-4, IL-13, TSLP, and IL-33, promoting eosinophil and mast cell infiltration." (PMID 41479908, 2025). "A meta-analysis of studies evaluating TSLP concentrations in the blood of patients with atopic dermatitis revealed that serum TSLP levels are significantly elevated in individuals with AD compared to controls." (PMID 39860604, 2025). "The suppression of epidermal hyperplasia and reduction in serum TSLP levels by PCG treatment in the DNFB-induced atopic dermatitis mouse model suggest that PCG can attenuate TSLP level by suppressing PAR2-mediated inflammatory signaling." (PMID 41009488, 2025). "At barrier surfaces, such as the skin, lungs, and intestines, TSLP can trigger allergic diseases such as atopic dermatitis and bronchial asthma." (PMID 40787610, 2025). "Conversely, children and adults with atopic dermatitis exhibited significantly elevated serum TSLP levels compared to healthy individuals." (PMID 39940994, 2025). "TSLP, a keratinocyte-derived cytokine central to the immune response in atopic dermatitis, was substantially elevated in the serum of DNFB-treated mice." (PMID 41009488, 2025). "Thymic stromal lymphopoietin (TSLP) is a key epithelial‐derived cytokine implicated in the initiation of type 2 inflammation and pruritus, especially in disorders such as atopic dermatitis." (PMID 41388848, 2025).
atopic dermatitis (continued). "In summary, pneumococcal Δpep27 immunization alleviated allergic dermatitis symptoms by upregulating Tregs and epithelial barrier functions and suppressing TSLP and Th2 to relieve allergic dermatitis symptoms." (PMID 39066375, 2024). "Fu reported that OS can reduce atopic dermatitis in mice by restraining TSLP produced by keratinocytes and that OS can also inhibit the Th2 cell response." (PMID 39334402, 2024). "Together with the activation of innate lymphoid 2 cells (ILC2s), TSLP initiates the innate and adaptive immune responses of atopic dermatitis." (PMID 39202657, 2024). "Dieckol and phloxine O reduce atopic dermatitis-like inflammatory symptoms by inhibiting TSLP production." (PMID 39202657, 2024). "Another important factor, in addition to Artemin, involved in the pathogenesis of atopic dermatitis is thymic stromal lymphopoietin (TSLP), which is known to activate dendritic cells and promote Th2-type immune responses." (PMID 38181031, 2024). "Our study highlights the potential of natural compounds targeting thymic stromal lymphopoietin (TSLP) as promising therapeutic agents for managing atopic dermatitis (AD) and related inflammatory conditions." (PMID 39766227, 2024). "On the other hand, Treg suppression worsened atopic dermatitis through the upregulation of TSLP and Th2 and the repression of epithelial barrier function compared with the non-suppressed pneumococcal Δpep27 group." (PMID 39066375, 2024). "Keratinocytes in atopic dermatitis skin also express high levels of thymic stromal lymphopoietin (TSLP), a member of the cytokine family." (PMID 39202657, 2024). "Other cells responsible for itching and pain in atopic dermatitis include keratinocytes, which secrete TSLP, and endothelin-1 (ET-1) and NGF, which are factors that activate nerves and lead to increased sensitivity and dysfunction of the skin barrier." (PMID 38672221, 2024). "Many polyphenols, including curcumin, baicalin, and quercetin, have been found to inhibit the production of TSLP and IL-33 in atopic dermatitis mice models and human keratinocyte models of the disease." (PMID 38931338, 2024). "IL-33 is released along with TSLP by keratinocytes in response to skin barrier damage and inflammation observed after mechanical injury and scratching or in atopic dermatitis." (PMID 36904070, 2023). "Cytokines such as Thymic Stromal Lymphopoietin (TSLP), Interleukin-33 (IL-33), and Interleukin-4 (IL-4) are commonly expressed in atopic dermatitis and play roles in causing skin itching." (PMID 37762597, 2023). "Thymic stromal lymphopoietin (TSLP) is critical in developing allergic responses, including atopic dermatitis (AD)." (PMID 37515689, 2023). "Overexpression of TSLP in skin keratinocytes and elevated level of TSLP in serum has been observed in patients with atopic dermatitis." (PMID 36904070, 2023). "The expression levels of IL-33 and TSLP obviously increased in the back skin of mice with atopic dermatitis induced by HDM treatment." (PMID 36077570, 2022). "TSLP activates dendritic cells to differentiate helper T cells into Th2 cells, which is critical to induce the symptoms of atopic dermatitis." (PMID 35513696, 2022). "Initially, research about TSLP mainly focused on allergic disorders, such as allergic asthma, atopic dermatitis (AD), allergic rhinitis, eosinophilic esophagitis, and food allergies." (PMID 36046760, 2022). "Chronic TSLP release by keratinocytes responding to cellular and tissue damage instigates type 2 immune response that leads to atopic dermatitis." (PMID 35432341, 2022). "In this study, we found that ghrelin alleviates atopic dermatitis (AD)-phenotypes through suppression of thymic stromal lymphopoietin (TSLP) gene activation." (PMID 35409338, 2022). "PAR2-triggered release of TSLP can stimulate sensory neurons to evoke the itch response in allergic diseases such as atopic dermatitis, in a TSLPR- and TRPA1-dependent manner." (PMID 35432341, 2022).
atopic dermatitis (continued). "We and others have shown that TSLP is expressed in atopic dermatitis and activates DC to promote a Th2 response." (PMID 34983927, 2022). "In FITC-induced atopic dermatitis mice, 7-Met reduced Th1 cytokines production and regulated Th1/Th2 balance by downregulating the secretion of thymic stromal lymphopoietin (TSLP) via inactivation of the NF-κB pathway." (PMID 35610286, 2022). "TSLP expression has also been revealed to be upregulated in the lesional epidermis of atopic dermatitis patients, compared to the levels found in the epidermis of healthy patients." (PMID 35159975, 2022). "Vitamin D3 also induces the expression of TSLP in keratinocytes, which leads to the development of an atopic dermatitis-like phenotype." (PMID 35432341, 2022). "TSLP expression is increased in the skin of patients with atopic dermatitis and in mouse models of atopic dermatitis." (PMID 36613861, 2022). "Patients with atopic dermatitis have a cytokine profile characterised by abnormal levels of interleukins 4, 12, 13, 18, 22, 31 and 33; thymic stromal lymphopoietin; and interferon gamma." (PMID 35582626, 2022). "High TSLP expression is observed in a broad spectrum of skin lesions of atopic dermatitis, psoriasis, Netherton syndrome, and keloid." (PMID 35432341, 2022). "Continuous skin barrier disruption, characterized by atopic dermatitis, facilitates epicutaneous sensitization, which accelerates TSLP expression in keratinocytes." (PMID 35432341, 2022). "In human, TSLP regulates allergic inflammation at barrier organs such as skin and lungs and plays a key role in their physiopathology including atopic dermatitis and asthma." (PMID 33652749, 2021). "PAR2 signaling activates histamine-independent itching pathways, like the release of pruritogenic mediators and increased expression of TSLP, and histamine antagonists are known to be less effective as treatment for atopic dermatitis-related itch." (PMID 34208434, 2021). "The expression level of TSLP, a key factor for promoting Th2 response in atopic dermatitis, was elevated by approximately 9.8-fold in the skin of LBE group mice (71,974 ± 1066/2 × 107 pixels) than in the skin of control group mice (6659 ± 343/2 × 107 pixels)." (PMID 34946332, 2021). "The researchers sensitized mice using OVA and TSLP via the transdermal route (alone or in combination), resulting in the development of atopic dermatitis." (PMID 34301307, 2021). "Consistent with our findings in lymphedematous skin, keratinocytes are significant producers of TSLP, and the expression of TSLP increased the skin lesions of patients with atopic dermatitis." (PMID 34571811, 2021). "In patients with atopic dermatitis, higher levels of basal AP-1 expression are found together with elevated TSLP expression, which maintains a TH2-polarised inflammatory milieu." (PMID 34833113, 2021). "In other studies, osthole inhibited atopic dermatitis chronic itch by directly downregulating TSLP production from keratinocytes or activating warm-temperature Ca2+-permeable TRPV3 channels." (PMID 34691215, 2021). "One of the initial cytokines expressed upon skin barrier breach and during atopic dermatitis is TSLP." (PMID 34833113, 2021). "Thymic stromal lymphopoietin (TSLP) is an epithelial cell-derived cytokine that acts as a critical mediator in the pathogenesis of atopic dermatitis (AD)." (PMID 33919431, 2021). "TSLP is a well-known initiator of allergic T-helper 2 (Th2) responses, which are hallmarks of atopic dermatitis (AD)." (PMID 34833113, 2021). "Originally, it was implicated in atopic dermatitis and in a variety of other allergic reactions via TH2-cells, but emerging evidence indicates that TSLP is also involved in chronic inflammatory and autoimmune disorders (e.g., psoriasis) and in several cancers." (PMID 32927792, 2020). "TSLP, a keratinocyte cytokine that is important in atopic dermatitis pathogenesis, also plays a key role in sensitization through the skin." (PMID 33488627, 2020).